CLU (clusterin)
Diseases named in the same sentence as CLU in open-access papers (continued):
Sharing a sentence is not in itself a finding about the gene and the disease.
tumor (continued). "Moreover, CLU seems to modulate tumor progression and metastasis by mediating the components of the TME." (PMID 37686218, 2023). "The ability of clusterin to promote tumor invasion is based on epithelial-mesenchymal transition (EMT) induction, a process by which epithelial cells transform into mesenchymal tissue, losing the ability to adhere and gaining the possibility of moving to other parts of the body." (PMID 36071866, 2022). "Scientific studies reported that elevated clusterin expression in the ccRCC tumor tissue may correlate with shorter patient survival times." (PMID 36071866, 2022). "Clusterin can play a variety of functions in carcinogenesis and tumor invasion processes." (PMID 36071866, 2022). "It was noticed that increased expression of the CLU gene occurs in treatment-resistant neoplasms." (PMID 36071866, 2022). "On the other hand, it has also been suggested that in some neoplasms, CLU concentration in serum and/or tissue may become an early metastasis biomarker." (PMID 36071866, 2022). "The TIMER2 method was utilized to analyze CLU expression status across diverse tumor types in TCGA." (PMID 36685863, 2022). "With its proapoptotic properties, the nuclear form of clusterin present in neoplastic cells inhibits tumor progression, whereas secretory clusterin performs chaperone activity and may contribute to metastasis formation." (PMID 36071866, 2022). "Specifically, the ratio of CLU+/αSMA+ CAFs and the ratio of CLU+/HLA-DR+ CAFs was higher in BRCA-mut tumors compared to BRCA-WT tumors, suggesting that germline mutations in the cancer cells alter tumor CAF compositions." (PMID 36316305, 2022). "We conclude that CLU is expressed lower in most cancers than non-tumor tissues." (PMID 36685863, 2022). "The correlation between iCLU and tumor progression has also been demonstrated; thus, clusterin may become a prognostic and predictive CRC biomarker." (PMID 36071866, 2022). "In addition, we sought to explore the role of extracellular chaperones, especially of clusterin which is one of the most prominent in the extracellular space, in proteostasis and signaling transduction in the tumor microenvironment." (PMID 34360868, 2021). "Consistent with in vitro cell assays, in mice, tumors formed by PRKD3‐KO TNBC cells show significantly reduced tumor volumes and weights compared to those formed by parental cells, and either ectopic (over)expression of CLU or PRKD3 in PRKD3‐KO TNBC cells can restore TNBC tumor growth." (PMID 33643800, 2021). "In conclusion, we define PRKD3 to be a key regulator of CLU in promoting TNBC tumor growth, and provide new promising targeted therapies against CLU pathway via targeting CLU and PRKD3 as well as serum sCLU as a blood‐based biomarker for efficient management of TNBC." (PMID 33643800, 2021). "PRKD3 directly binds and stabilizes CLU to promote TNBC tumor growth." (PMID 33643800, 2021). "Elevated production of clusterin antigen, if secreted from tumor cells, may be detected in body fluids, such as serum." (PMID 33356806, 2021). "Previous research has reported that CLU could regulate the proliferation and invasion of vascular smooth muscle and tumor." (PMID 33874952, 2021). "We here identified CLU as a new TSG in LUAD which was related to tumor progression." (PMID 34001209, 2021). "CLU may be tumor-suppressive at the initial stages of carcinogenesis and tumor-permissive at late stages or in therapy-resistant cancers." (PMID 32268584, 2020). "Our RNA sequencing following BIX-01294 treatment revealed upregulation of the established NB tumor suppressors CLU, but also other putative tumor suppressors not previously associated with NB." (PMID 32537432, 2020). "Moreover, elevated CLU mRNA was closely related to tumor stage, lymph node metastasis and response to OXA (P < 0.05)." (PMID 32039450, 2020). "To evaluate the tumor suppressive role of CLU in vivo, we used xenograft tumor model." (PMID 33052230, 2020).
tumor (continued). "In our study, the expression of CLU increased, which may be due to MF as an inert tumor, CLU plays an inhibitory role on MF in the early stage, and on the other hand, it indicates the prognosis of the disease." (PMID 33299887, 2020). "Interestingly, changes in serum level and expression of CLU were closely correlated with tumor progression." (PMID 33184463, 2020). "Growing evidences have demonstrated that the over-expression of CLU in malignancies may contribute to tumor progression." (PMID 32039450, 2020). "The studies confirmed the hypothesis that CLU could indeed act as a tumor suppressor gene by knockout of the CLU gene." (PMID 33299887, 2020). "Our study leverages data from plasma RNA and CTCs, published studies and focused data mining, to propose a testable model in which high concentration of PF4 induces platelet attraction into the tumor microenvironment and regulates expression and/or availability of CLU, CCL5, TGFB1, SRGN and SPARC." (PMID 31215484, 2019). "CLU was mainly localized to tumor cells but the protein apparently was readily secreted." (PMID 28902909, 2017). "However, ISH revealed that mainly tumor cells expressed CLU mRNA, indicating that CLU protein was secreted from tumor cells into extracellular matrix." (PMID 28902909, 2017). "Changes in CLU expression were related to tumor stage and grade." (PMID 26988917, 2016). "Furthermore, recent studies have shown that CLU is involved in various biological functions, such as cell death, tumor progression and neuro-degenerative disorders." (PMID 25695263, 2015). "The same also applies to tumour recurrence, which, though present in our series, were too limited in number to allow statistical analyses and, above all, seemed more strictly related to tumour size and extra capsular spread than to Clusterin expression." (PMID 25934174, 2015). "In both cases, CLU up-regulation was associated with increased cancer cell survival, suggesting that CLU over-expression may contribute to increased tumour cell survival." (PMID 25934174, 2015). "CLU protein was predominantly detected in cytoplasm of tumor cells." (PMID 25609201, 2015). "This study suggested that elevated levels of CLU in several human cancers might promote tumour progression by interfering with pro-apoptotic pathways by interaction with activated Bax, thereby inhibiting cytochrome C release and apoptosis." (PMID 25934174, 2015). "Indeed, decreased Ki67 expression and increased apoptotic rates with combined ZOL and CLU inhibition suggests that delayed tumor progression resulted from both inhibition of tumor proliferation and enhanced treatment-induced apoptosis." (PMID 25138053, 2014). "Indeed, several cytoprotective chaperones such as Heat Shock Protein-27 (Hsp27) or clusterin (CLU) are reported to play a protective function in tumor cells under stress condition such as conventional or targeted therapies." (PMID 25138053, 2014). "On the other hand, at more advanced stages of tumor progression, during which cells are exposed to more severe stressors, GRP78 suppresses caspase 7 activation and interacts with ER stress-induced protein chaperones such as clusterin to promote cell survival and further tumor development." (PMID 24868470, 2014). "However, CLU inhibition using OGX-011 significantly but partially re-sensitzed MG63R tumor cells (in blue) to ZOL inhibitory effect by decreasing cell viability by 25% compared with MG63R treated with ScrB ASO." (PMID 25138053, 2014). "Clusterin may play a key role during tumorigenesis and tumor progression of ESCC and it could be applied in clinical work as a tumor marker and prognostic factor." (PMID 25574066, 2014). "One of the plausible explanations is that clusterin may confer an anti-apoptotic effect on tumor cells once they are detached from the original site, and thus prolongs cell survival under unfavorable conditions in the metastatic process." (PMID 22799602, 2012).
tumor (continued). "Furthermore, serum clusterin levels were above the cut-off value in 5 of 12 HCCs (41.7%) in whom both serum AFP and PIVKA-II were within their cut-off values, suggesting that clusterin is complementary to the conventional two representative HCC tumor markers." (PMID 22957256, 2012). "Although clusterin restrains proliferation of untransformed epithelial cells and acts primarily as a tumor-suppressor during early stages of carcinogenesis, when re-expressed in advanced cancers, clusterin might promote tumor growth." (PMID 21464964, 2011). "The relative clusterin mRNA value was 0.764 ± 0.18 for tumor and 0.14 ± 0.11 for backgrounds." (PMID 21609464, 2011). "Moreover, CLU was detected more strongly expressed in invasive BTCC compared with the expression in superficial BTCC and the pathologic stage and tumor grade showed close associations with CLU expression." (PMID 21496341, 2011). "Thus, we identify a novel role for clusterin in enabling pituitary gonadotroph tumor cell proliferation arrest." (PMID 21464964, 2011). "Thus, clusterin was down-regulated, and its expression inversely proportional to tumor grade/or metastatic stage." (PMID 21464964, 2011). "Expression of another tumor suppressed protein, clusterin, was 70% less in the As2O3 and DDP treated A549 cells than in control cells, and in H460 cells, clusterin expression was 90% less with treatment with the combination of As2O3 and DDP than in control cells." (PMID 19664237, 2009). "We have previously suggested that CLU might be a potential tumor-suppressor gene acting through its nuclear form nCLU." (PMID 18974881, 2008). "As a matter of fact, we and others have found that CLU is down-regulated during CaP progression, suggesting that it might act as a tumour-suppressor factor." (PMID 18974881, 2008). "In addition, our studies have firmly established a role for clusterin as a cell survival gene that is increased after tamoxifen therapy and chemotherapy to inhibit tumor cell death." (PMID 18078515, 2007). "Clusterin levels may vary in different types of cancer and depending on the tumor type." (PMID 37834086, 2023). "In fact, due to the dual role of clusterin as a tumor suppressor and a tumor promoter, currently, it remains uncertain whether cancer specifically expresses only the anti-apoptotic form of CLU or if pro-apoptotic nCLU isoforms are consistently suppressed in different types of cancers." (PMID 37239129, 2023). "Importantly, we provide both in vitro and in vivo preclinical experimental evidences to show the efficiency of CLU silencer (OGX‐011) and PRKDs inhibitor (CRT0066101) treatment in TNBC tumor growth suppression, suggesting targeting CLU pathway will be promisingly efficient for treatment of TNBC." (PMID 33643800, 2021). "Therefore, we believe that the role of CLU should be divided into stages which play a role in tumor suppressor genes in the early stage but promotes the development of cancer in the later stage when the tumor suppressor factor is inactivated or acquiring improper activity like pRb." (PMID 33299887, 2020). "Moreover, in primary tumor and metastases, the expression of CLU and p65 is inversely correlated." (PMID 31885575, 2019). "Of note, an even stronger expression of these proteins was detected in the cancerous lesions of age-matched TRAMP/CLUKO, suggesting the hypothesis that one possible mechanism by which CLU slows down tumor spreading in TRAMP mice might also involve limiting NF-κB activity." (PMID 31885575, 2019). "Thus, clusterin may play a key role during tumorigenesis and tumor progression of ESCC and it could be applied in clinical work as a tumor marker and prognostic factor." (PMID 25574066, 2014). "However, ZOL triggers the elevation of heat shock proteins (Hsp), including Hsp27 and clusterin (CLU), which could enhance tumor cell survival and treatment resistance." (PMID 25138053, 2014).
tumor (continued). "These seemingly disparate results may be due to a lack of knowledge regarding the causal relationship between clusterin expression and tumor cell apoptosis, which can affect patient survival." (PMID 22799602, 2012). "We constructed a spatial transcriptomic map of CRC development and further defined molecular differences between tumor and normal tissues, as well as differences validated, in part, through known cell markers like S100A6 and CLU." (PMID 41009818, 2025). "CSCs, which drive tumor initiation and progression, can originate from both LGR5+ stem cells and LGR5– RSCs (e.g., those expressing clusterin (CLU) and LY6A)." (PMID 39656543, 2025). "Inverse correlations were found between the IHC scores of PROS1 (P = .024), CLU (P = .010), and LRG1 (P = .038) and PTC patients with higher tumor classification, respectively." (PMID 40797389, 2025). "Conversely, CLU, SOCS3, and genes from the HLA-DRB family were significantly highly expressed in NSTAS tumor cells." (PMID 40786043, 2025). "The expression levels of PROS1 (P = .001), CLU (P < .001), and LRG1 (P = .002) were significantly lower in PTC patients with large tumor size (>2 cm) than in small tumor size patients (≤2 cm), respectively." (PMID 40797389, 2025). "The glycoprotein clusterin (CLU) is involved in cell proliferation and DNA damage repair and is highly expressed in tumor cells." (PMID 39627493, 2025). "Clusterin (CLU) protein is involved in various pathophysiological processes including carcinogenesis and tumor progression." (PMID 38667280, 2024). "In breast cancer, CLU collaborates with eHsp90α to activate key signaling pathways, promoting EMT, migration, and tumor metastasis." (PMID 38667280, 2024). "In the bulk sequencing data, we stratified the tumor samples into two groups according to the median expression of the marker genes (SFRP4, CLU, OGN)." (PMID 38686196, 2024). "For example, the tumour cell expressed genes CD24, CLU, and SLPI35–37 and the infiltrating cell expressed genes GPNMB, MGP, GPX3, and MFAP438–41 have all been previously associated with poor prognosis and chemotherapy resistance in HGSOC." (PMID 38570491, 2024). "This revealed several strong putative interactions between GBM tumor cell ligands and macrophage receptors that were conserved over the different co‐cultures, including APP:CD74, CD99:PILRA, PTN:ALK, and CLU:TREM2." (PMID 37791581, 2023). "This are the case with the high expression of CLU and SLPI, upregulated genes in the tumor samples that are correlated to cell migration and invasion capacity, favoring metastasis and therefore resulting in more severe disease." (PMID 36982287, 2023). "In a recent study, PKD3 was found to inhibit lysosomal-dependent degradation of the stress-activated chaperone clusterin, thereby promoting clusterin secretion and TNBC tumor growth in a xenograft mouse model." (PMID 37293129, 2023). "Loss of EZH2 facilitates reduction of H3K27me3 levels and activation of clusterin (CLU) and nerve growth factor receptor (NGFR), which are tumor suppressive genes in NB." (PMID 35392988, 2022). "According to the UALCAN database, a considerable increase in methylation levels was found across CLU in LUAD, CHOL, HNSC, ESCA, BRCA, PRAD, and LUSC tissues compared to that in non-tumor tissues." (PMID 36685863, 2022). "The result showed that the lower mRNA expressions of C3, C5, CFB, and CLU were correlated with more advanced cancer stage, while the lower mRNA expressions of C1S, C8B, CFI, MBL2, and C4BPA were correlated with higher tumor grade in HCC patients." (PMID 34813686, 2022). "It is assumed that the expression of the CLU gene promotes cell survival, which may have two effects in the context of the whole organism, either beneficial, promoting neuronal survival by combating toxic agents, or detrimental, enabling tumor cells to survive." (PMID 36071866, 2022).
tumor (continued). "In the cell subsets of tumor samples, FN1, CLU, and ANXA1 were high expressed in tumor cells and low expressed in myeloid cell and fibroblast." (PMID 35359404, 2022). "The tumor stains for one or more of the FDC markers including CD21, CD23, CD35, D2-40, clusterin, CXCL13, FDC-secreted protein and Serglycin." (PMID 35941667, 2022). "In our collected tumor samples from TNBC patients, CLU and PRKD3 protein level are found to be significantly positively correlated, supporting the positive regulatory relation between CLU and PRKD3." (PMID 33643800, 2021). "In our study, IPT-like FDCS tumor cells expressed CD21 and CD35, while partly expressing CD68, smooth muscle actin, vimentin, and clusterin." (PMID 33731032, 2021). "To further confirm the efficiency of targeted therapy against CLU pathway for treatment of TNBC, we generated patient‐derived TNBC organoid assays and patient‐derived xenograft (PDX) TNBC tumor murine models." (PMID 33643800, 2021). "The positivity of CLU and PRKD3 in TNBC is found to be significantly correlated in clinical TNBC tumor samples." (PMID 33643800, 2021). "First, we examined CLU and PRKD3 protein expression level in clinical TNBC tumor samples from patients by immunohistochemical analysis." (PMID 33643800, 2021). "CLU and PRKD3 protein level are significantly elevated and positively correlated in collected TNBC tumor samples." (PMID 33643800, 2021). "CLU silencer (OGX‐011) and PRKDs inhibitor (CRT0066101) can both result in impressive tumor growth suppression in vitro and in vivo, suggesting targeting CLU and its key regulator‐PRKD3 are promisingly efficient against TNBC." (PMID 33643800, 2021). "In conclusion, CLU over-expression is observed in plasma specimens from HCC cases, and its levels are related to tumor stage and lymph node metastasis." (PMID 32039450, 2020). "The GEO2R web tool was used to compare the mRNA expression of CLU and p65 in the microarray dataset GSE6919, which comprises primary and metastatic prostate tumors, normal prostate tissue adjacent to tumor, and normal prostate tissue from healthy donors." (PMID 31885575, 2019). "Of these, the most significantly upregulated molecule in tumor stroma was a gene product of integrin alpha-1 (ITGA1), and the most upregulated molecule in tumor parenchyma is a product of the CLU gene (i.e., clusterin)." (PMID 29899869, 2018). "This indicates that clusterin induce NSCLC cell EMT, which probably has a close relation with tumor metastasis and drug resistant." (PMID 28954633, 2017). "The clinical investigation showed that CLU, MMP-9 and VEGF were positively correlated with the tumor-node -metastasis (TNM) classification." (PMID 26716898, 2016). "We next investigated the inhibitory effect of eIF3f on CLU expression and Akt and ERK signaling pathway in tumor tissues harvested from control and eIF3f treated mice." (PMID 26988917, 2016). "In this study, we examined methylation patterns of ten tumor-associated genes (RASSF1A, GSTP1, RIZ1, SOCS1, TNFRSF10C, hTERT, NRG1, CLU, miR-203, miR-663) and of the LINE-1 repetitive element in 45 HCC and 17 matching non-tumor livers." (PMID 25889455, 2015). "Overexpression of CLU in HCC tissues was correlated with shorter overall survival and higher tumor recurrence." (PMID 25609201, 2015). "Taken together, these results suggest that the increased tumor growth and liver metastatic capacity conferred by L1 in CRC cells requires the elevated expression of CLU that is induced by L1." (PMID 26399194, 2015). "Among the most abundant sialoglycoproteins (median intensity >150,000) over-expressed in tumor cells, those with the largest Effect size (Effect size >5.0) include SLC1A3, PTPRZ1, GPR56 and CLU." (PMID 25360666, 2014). "Other interesting afferent crosstalk pairs involved LRP8 receptor in tumor activated by a double stimulus of RELN and CLU proteins secreted by adjacent mucosa, and VIP, an intestinal peptide that causes vasodilatation, linked to MME receptor in tumor cells." (PMID 24597571, 2014).